FASN (fatty acid synthase)
Diseases named in the same sentence as FASN in open-access papers (continued):
Sharing a sentence is not in itself a finding about the gene and the disease.
tumor (continued). "This facilitates nuclear translocation of PKM2, enabling activation of fatty acid synthase (FASN) expression via STAT3 phosphorylation, thereby promoting de novo lipogenesis, tumor proliferation, and vasculogenic mimicry." (PMID 40842995, 2025). "Our results demonstrated a significant upregulation of fatty acid metabolism and fatty acid synthase (FASN) in the KAR tumours, with ARID1A directly regulating FASN expression." (PMID 40621620, 2025). "Pharmacological inhibition of acetyl-CoA metabolism via PDC-E2 blockade, as well as suppression of palmitate synthesis through FASN inhibition, resulted in a significant reduction in CD47 expression in tumour cells." (PMID 41163221, 2025). "Our research establishes a strong correlation between high FASN expression in CRC, preservation of CSC function, and tumor progression." (PMID 40901481, 2025). "By targeting enzymes such as LDHA, GLUT1, HK2, PKM2, GLS1/2, FASN, ACLY and ACC, researchers have demonstrated the feasibility of disrupting tumor bioenergetics and biosynthetic machinery." (PMID 40941984, 2025). "Like other members of the USP family, USP38 can regulate FASN protein expression, indicating that USP38 has the potential to indirectly regulate lipid metabolism in the tumor microenvironment." (PMID 40936898, 2025). "Taken together, our findings propose a novel mechanistic axis—centered on FASN and RUNX2—linking metabolic enzymes to protein lactylation and downstream tumor-promoting processes." (PMID 40703521, 2025). "MCF-7 and MCF-7 TamR BC cell lines, as tamoxifen sensitivite and resistance in vitro models, were used to explore the correlation between FASN/LDHA expression and tumor aggressiveness." (PMID 39044184, 2024). "Predictably, images of the liver and H.E. staining showed that overexpression of SIAH1 inhibited tumor growth and intrahepatic metastasis, and immunohistochemistry was used to analyze the expression of SIAH1, ADRM1, UCHL5, FASN, and FSCN1." (PMID 39075049, 2024). "After subcutaneous tumor irradiation for five treatment cycles, we observed a significant reduction in tumor volume upon silencing of PITPNC1 and FASN." (PMID 38291470, 2024). "FASN regulates one of the reactions shown to be upregulated in high-grade models (MAR02174), and the expression of this enzyme has already been correlated with the grade of clear-cell OC48, which implies a similar association could exist for high-grade tumours." (PMID 39181893, 2024). "BHLHE40 has been reported to have tumor suppressive functions and has been shown to affect energy metabolism by regulating PGC-1α, SREBP-1c, PKLR, PCK2, FASN, and PPARγ." (PMID 38301894, 2024). "To further verify the in vivo contribution of the POU6F2-AS1/FASN axis to promoting CRC cell growth and lipogenesis, we performed HCT116 cell growth assays and mouse tumour xenograft model experiments." (PMID 38491348, 2024). "And immunofluorescence showed the location of CBR4 and FASN in GEP‐NETs cell lines, and lower levels in tumor cells than normal cells." (PMID 39524139, 2024). "FASN inhibitors, such as orlistat and TVB-2640, have shown potential in preclinical studies by disrupting lipid synthesis and thereby depriving tumor cells of essential components." (PMID 39596558, 2024). "Knocking out key enzymes related to fatty acid synthesis, such as FASN, ACC, and ACLY, can reduce cell proliferation and induce apoptosis in tumor cells." (PMID 39609317, 2024). "The expression of fatty acid synthase (FASN), a key enzyme in the last step of catalytic FA synthesis, is significantly higher in a variety of human tumor cells than in corresponding normal cells." (PMID 38184562, 2024). "In this study, we uncovered a novel function of the palmitoyltransferase ZDHHC21 as a tumor suppressor in DLBCL and identified ZDHHC21 as a key regulator of fatty acid synthetase (FASN) S-palmitoylation for the first time." (PMID 38195819, 2024).
tumor (continued). "In this study, we elucidate the connection between FASN and LDHA, pivotal metabolic genes, and their correlation with tumor grade and therapy response using datasets from public repositories." (PMID 39044184, 2024). "Immunohistochemical and immunofluorescence and flow cytometry staining demonstrated that the proportion of CD8+ T cells and IFN-γ+ CD8+ T cells in the tumor tissue increased after silencing PITPNC1 and FASN." (PMID 38291470, 2024). "SREBP1, FASN, and 4-HNE expression was detected by IHC on PCa tissue microarrays (TMA) slides, which included 80 PCa tumor tissues and paired adjacent normal tissues." (PMID 39309439, 2024). "FAs produced by de novo fatty acid synthesis via fatty acid synthase (FASN) or by the exogenous uptake of lipids from the TME (e.g., through the scavenger receptor CD36) fuel rapid tumor cell growth." (PMID 39667305, 2024). "Consistently, a significant decrease in the mRNA levels of PPARa, ACLY, FASN, ACSL1 and ACSL5 was observed in the livers of C26 tumor-bearing mice compared with control mice." (PMID 38245529, 2024). "Tumor cells engage in de novo synthesis of fatty acids, which is mainly contributed by ATP-citrate lyase (ACLY), acetyl-CoA carboxylase (ACC), and fatty acid synthase (also known as FASN)." (PMID 38216787, 2024). "The combination of two mechanistically distinct FASN inhibitors, namely orlistat and TVB-2640, with an anti-PD-L1 antibody was found to robustly suppress tumor growth in vivo." (PMID 39349429, 2024). "In this way, FASN methylation level could potentially be useful in future clinical trials of FASN inhibitors because DNA methylation is often more robust to preclinical variables compared with protein biomarkers, and may even be measured accurately in circulating tumor DNA." (PMID 38112617, 2024). "For example, increased ad libitum FASN contributes to the functional maturation of both Treg and TAM-M2 cells; conversely, inhibition of FASN impairs the tumor-promoting effects of TAMs by suppressing TNF-α, IL-6, IL-10, and ROS expression." (PMID 39227970, 2024). "Previous researches have proven that the effect of a FASN inhibitor (TVB-3166) on carcinogenic signals and gene expression enhances the antitumor efficacy of various xenograft tumor models." (PMID 38218866, 2024). "Simultaneously, examination of the apoptosis rate of tumor cells in the co-culture system indicated an increase in tumor cell apoptosis following the knockdown of PITPNC1 and FASN." (PMID 38291470, 2024). "Since the survival and differential expression analysis results showed that both FASN and RAC3 were highly expressed in tumor tissues, the next step was carried out." (PMID 39659999, 2024). "In summary, SREBP and FASN ultimately lead to the impaired maturation of Tregs, and SREBP inhibition promotes anti-tumor responses in Tregs." (PMID 38302980, 2024). "The expression of FASN, GFPT1, OGT and O-GlcNAc is much higher in tumor tissues as compared to normal mucosa." (PMID 38732103, 2024). "A number of studies have shown that the targeting of lipid metabolism enzymes, such as FASN and CD36, restored the anti-tumor effect of CD8 + T cells and enhanced the effect of immunotherapy." (PMID 38302980, 2024). "Since FAs are limited in the human body for fast-growing tumors, many tumor cells synthesize unsaturated FAs by de novo synthesis pathway, modulated by several key enzymes such as ACLY, SCD, FASN, and ACC." (PMID 38560498, 2024). "FASN and ACLY immunohistochemistry tumor staining of PDX samples validated what it was previously observed in vitro." (PMID 38425123, 2024). "Regarding the mechanism of the tumor-suppressing role of TC2N, we show that TC2N restrains fatty acid synthesis by regulating FASN at protein level." (PMID 38167440, 2024). "The protein stability of ATP-citrate lyase (ACLY) and fatty acid synthase (FASN) is controlled through the dynamic processes of acetylation and deacetylation, thereby regulating de novo lipogenesis and tumor growth." (PMID 39551780, 2024).
tumor (continued). "The binding of COP9 signalosome subunit 6 (CSN6) to FBXW7β inhibits the degradation of fatty acid synthase (FASN), promoting lipogenic CRC and tumor progression." (PMID 39749199, 2024). "Increased expression of fatty acid synthase (FASN), which catalyzes de novo synthesis of long-chain fatty acids, has been described in several tumor types, while its inhibition has been shown to have antitumor activity." (PMID 36982278, 2023). "Other FASN inhibitors like TVB-3166, Fasnall, and AZ12756122 also promote enhanced anti-tumor effects in combination therapies." (PMID 37700339, 2023). "Expression of tumor biomarkers, such as PCNA and FASN, was also suppressed by CAPE and CAPPE in tumor tissue." (PMID 36765950, 2023). "Two PDX cases containing high CSN6 with concurrent high FASN (CRC5647, CRC2849) and two other PDX cases containing low CSN6 with concurrent low FASN (CRC4232, CRC3707) were selected for tumor growth studies under the orlistat treatment." (PMID 37202390, 2023). "Consistent data revealed that de novo lipogenesis supported by FASN in the TME, supplies tumor cells with energy, which enhances their rapid proliferation." (PMID 37760840, 2023). "Inhibitors of fatty acid synthase (FASN), an enzyme involved in de novo fatty acid synthesis, have exhibited anti-tumor effects and enhanced sensitivity to chemotherapy in preclinical studies." (PMID 37880766, 2023). "Another FASN inhibitor that has been widely investigated is orlistat, which is an anti-obesity drug approved by the FDA that has been proven to be effective in tumor biology." (PMID 37056351, 2023). "The enhancement of the de novo fatty acid synthesis pathway is the main manifestation of lipid metabolism reprogramming in tumor cells, which involves a variety of key enzymes, mainly including increased expression of ACLY, ACC, and FASN." (PMID 36994237, 2023). "To further validate CSN6-FASN axis in terms of clinical significance, we analyzed the protein levels of FASN and CSN6 in CRC cell lines or tumor tissues." (PMID 37202390, 2023). "Consistent with the findings in the tumor studies, TRIM21 mediates FASN ubiquitination and degradation in hepatocytes." (PMID 37249651, 2023). "Fatty acid synthase (FASN), the key enzyme in this pathway, is overexpressed in NSCLC, and inhibiting its expression can suppress tumor growth and induce apoptosis." (PMID 37894277, 2023). "Blocking FASN resulted in an apparent reduction in the migration and EMT activities of the tumor cells." (PMID 37159817, 2023). "CD36 inhibitors hinder tumor development, specifically metastasis and angiogenesis in the TME 238 and have shown synergistic effects in combination with the FASN inhibitors and anti-PD-1 therapy." (PMID 37064872, 2023). "Previous studies have shown that TVB-2640 and PF-05175157 can inhibit the expression of FASN and ACC in tumor cells, respectively." (PMID 37120513, 2023). "Having determined the differential FASN expression levels in PDAC and PCa, we performed a cell viability assay on four different cell lines, two for each tumor type." (PMID 36650542, 2023). "FASN-mediated DNL contributes to the functional maturation of Treg cells, while PD-1 expression in tumor-infiltrating Treg cells is also elevated, dependent on SREBP activation." (PMID 37700339, 2023).
tumor (continued). "The yarrow supercritical extract inhibits tumor growth in PC transplantation mice models by downmodulating SREBF1 and its downstream targets, SCD and FASN." (PMID 36699061, 2022). "Studies have shown that one of the early characteristics of tumor cells is the enhancement of FA biosynthesis, which is mainly manifested by the increased expression of ACC, FASN, CD36, and FABPs." (PMID 35743814, 2022). "FASN inhibition reduces FAS, induces malonyl-CoA accumulation, and inhibits CPT1-mediated FAO, leading to cell cycle arrest and apoptosis of tumor cells." (PMID 35743814, 2022). "In contrast to FASN, AC107027.3 expression was low in tumor tissues, and was positively correlated with overall survival." (PMID 35392075, 2022). "Additionally, FASN was significantly associated with tumor mutational burden (TMB) and microsatellite instability (MSI) in multiple malignancies, suggesting that it may be essential for tumor immunity." (PMID 36555243, 2022). "The p53R273 mutant increases the expression of FASN, ELOVL6 and SCD1, leading to an increased FA de novo synthesis via the MVP and tumor progression." (PMID 36551752, 2022). "The silencing of relevant genes, especially FASN and ACC, significantly inhibits tumor development by limiting lipogenesis." (PMID 36699061, 2022). "We next investigated the role of USP22-mediated stabilization of FASN in CRC cell proliferation and tumor growth." (PMID 36333288, 2022). "To further investigate the regulatory function and molecular mechanism of FASN in the tumor microenvironment, we analyzed the MSI and TMB of FASN." (PMID 36555243, 2022). "Considering that C75 showed relevant side effects, another compound was developed to inhibit FASN, C93, which promoted a remarkable growth reduction in NSCLC orthotopic xenograft tumors and prevented tumor growth in carcinogen-exposed mice." (PMID 35159223, 2022). "FASN upregulated in ESCC, and both knockdown and knockout of FASN significantly inhibited ESCC cell proliferation, which revealed a tumor exponent function for this gene in ESCC." (PMID 36106333, 2022). "Acetate can function as an epigenetic metabolite that induces H3 acetylation of H3K9, H3K27, and H3K56 at FASN and ACC promoters, which upregulates FASN and ACC expression and increases de novo lipid synthesis to promote tumour cell survival." (PMID 35215499, 2022). "The content of both ATP citrate lyase (ACYL) and fatty acid synthase (FAS), which are involved in the synthesis of FA, increased significantly in tumor biopsies when compared to NAT." (PMID 35534478, 2022). "ACSL3, EPAS1, FASN, GSTP1, LDHB, and NEDD4L were identified as the candidate genes through the intersection of tumor-related genes, DEGs, and ferroptosis-related genes." (PMID 35223835, 2022). "Pharmacological inhibition of FASN with the small molecule TVB-2640 impaired self-renewal and tumor growth ability of SCLC." (PMID 35898882, 2022). "The immunohistochemistry results suggested that the expression of TM4SF1, FASN, and IMPDH1 was significantly elevated in tumor tissue specimens, while the expression of KCNK5 and KCNJ15 was downregulated." (PMID 35480865, 2022). "A tumor gene, H-ras can upregulate mitogen-activated protein (MAP) kinase and PI3K signaling, which increases SREBP-1 and FASN levels to drive mammary epithelial cell malignant transformation and tumor virulence." (PMID 35912181, 2022). "Inhibition of SREBP-1 downregulates FASN and ACC levels, thereby reducing palmitic acid and stearic acid synthesis and notably inhibiting cell proliferation in the BxPC-3 transplantation tumor model." (PMID 36699061, 2022). "Two other novel FASN inhibitors, TVB-3664 and TVB-3166, show anti-tumor activity in many types of neoplasms in in vitro and in vivo tests, but, currently, there are no reports of their use in further clinical trials." (PMID 35628385, 2022). "Next, we conducted an IHC assay in shleptin-silencing xenograft tumor tissues to validate the expression patterns of SREBP1, FASN, and SCD1." (PMID 35628510, 2022).
tumor (continued). "Knockout or overexpression of FASN gene significantly downregulates or upregulates the resistance of PC cells to GEM, in which the acidic tumor microenvironment also plays a pro-drug resistance role (Zuzčák and Trnka, 2022)." (PMID 36699061, 2022). "The RT-qPCR results revealed that SREBF1 and FASN showed significantly high expression in ten IMPC and nine IDC-NOS tumor tissues, respectively (Student’s t-test, P = 0.013 and 0.037)." (PMID 34799559, 2021). "Fatty acid synthase (FASN), which synthesizes palmitate from acetyl-CoA and malonyl-CoA, is frequently overexpressed in tumor cells, where it inhibits apoptosis." (PMID 33530560, 2021). "On the other hand, elevated levels of FASN were found in prostates of transgenic mice of prostate adenocarcinoma (TRAMP) and its levels increased with age, tumor progression, and metastasis." (PMID 33166087, 2021). "In addition to increased expression of ACC and FASN, β‐catenin is also linked to mitochondrial dysfunction which could not be offset by an increased de novo synthesis of lipid in tumor cells." (PMID 34766135, 2021). "We observed the declined expression of lipid homeostasis regulating molecules like FASN, ACSS2, and SREBP1c in MJ exposed tumor cells." (PMID 33718176, 2021). "Inhibition of FASN has been observed to upregulate expression of CD36, which can compensate for the anti-tumor effects of FASN inhibition." (PMID 33514004, 2021). "POSTN binds to integrins through its Fatty Acid Synthase (FAS) domains and activates the Akt/PKB and the FAK-mediated signaling pathways, which together contribute to increased tumor invasion, migration, and metastasis." (PMID 33513753, 2021). "SREBP1c, which is the major factor upstream of FASN, is usually activated by the AKT/mTOR signaling pathway and plays an important role in tumor cell survival and progression." (PMID 34158007, 2021). "In fact, mRNA levels of enzymes of FA synthesis pathway was significantly increased in tumor cells, including ACLY, ACACA, and FASN." (PMID 34206240, 2021). "The impact of inhibited expression of FASN, ACSS2, and SREBP1c in MJ-exposed tumor cells was also investigated by assessing tumor cell membrane’s stability through examining the osmotic fragility." (PMID 33718176, 2021). "FASN inhibition significantly suppresses the expressions of TNF-α, IL-6, IL-10, and ROS in TAMs, thereby impairing their pro-tumor activity." (PMID 34742349, 2021). "In CRC, upregulation of lipid metabolic enzymes such as FASN and ACC leads to tumor progression and metastasis through activation of oncogenic pathways including Wnt, PI3K/AKT, AMPK/mTOR." (PMID 34200820, 2021). "Many of these proteins (FABP7, FASN and ELOVL2) are up-regulated in GBM patient-derived tumor stem cell cultures compared to more-differentiated adherent cells cultured in serum-containing medium." (PMID 34444824, 2021). "FASN, a downstream effector of PPARG, was elevated in OE orthotopic tumour samples, suggesting a metabolic effect of PPARG." (PMID 33654198, 2021). "Inhibition of fatty acid synthesis in vivo, both targeting ACACA with TOFA or FASN with either Orlistat or UB006, not only reduced tumor growth, but importantly led to neural differentiation, as assessed by expression of differentiation markers." (PMID 33659885, 2021). "For instance, inhibitors to Fatty Acid Synthase (FAS) as C75, orlistat, C93 have shown effects in stopping tumor growth of xenograft models." (PMID 34692471, 2021). "Among metabolic markers, the expressions of FASN and CPT1A were characterised by higher H-scores in tumour cells (median H-score = 210 and 240, respectively), in contrast to those in normal breast epithelium (respectively)." (PMID 32899149, 2020). "Pharmacological inhibition of FASN by orlistat (Xenical) (an FDA-approved anti-obesity drug) inhibits EGFR palmitoylation, limiting tumor cell survival." (PMID 32516941, 2020).